CCL2 (C-C motif chemokine ligand 2)
Diseases named in the same sentence as CCL2 in open-access papers (continued):
Sharing a sentence is not in itself a finding about the gene and the disease.
Arthritis (132 papers, 2005 to 2026). Inflammation of a joint. "Using in vitro cultured primary human osteoblasts and an in vivo rat CIA model, another study demonstrated that EGCG was able to ameliorate arthritis in rats, associated with reduced MCP-1/CCL2 and GRO/CXCL1 synthesized by osteoblasts." (PMID 26379475, 2015). "Separately, several synovial fluid biomarkers indicative of cartilage injury have been associated with development of arthritis, including the proinflammatory cytokine monocyte chemoattractant protein 1 (MCP-1), also known as chemokine C–C motif ligand 2 (CCL2)." (PMID 35476154, 2022). "Additionally, mice deficient for the Gpsm3 gene were protected from arthritis induced by anticollagen antibodies that reduced CCL2 and CX3CL1-mediated migration of myeloid cells." (PMID 30648118, 2018). "DA rats are widely used in arthritis research because of their enhanced susceptibility to arthritis compared to Wistar rats due to defect in oxidative burst in macrophages in response to CCL2 or other stimuli, which was demonstrated here and by others." (PMID 23658840, 2013). "The 1,407 genes with increased expression in DA and reciprocally decreased expression in DA.F344(Cia5a) congenics included pro-inflammatory cytokines and chemokines implicated in arthritis pathogenesis such as Il1b (5.17-fold on microarray, and 2.46-fold on qPCR), Il18, Mif, Ccl2, Ccl7 and Cxcl13." (PMID 23249408, 2012). "The alleviation of chikungunya-associated arthritis and myositis by treatment with the MCP-1/CCL-2 inhibitor Bindarit in mice also strongly suggests that monocytes-macrophages, the main targets in MCP-1/CCL-2 tissue tropism, are central to muscle and joint disease." (PMID 22479654, 2012). "However, most early arthritis genes in clusters C and D showed an expression peak later, at the acute phase of inflammation, and encoded chemokine receptors (Ccr2 and Ccr5) and chemokine ligands (Cxcl1, Ccl2, Ccl7, and Ccl9)." (PMID 15743466, 2005). "Elevated levels of CCL-2 are commonly observed in inflammatory diseases, such as arthritis, arthrosclerosis, and chronic infections." (PMID 40807308, 2025). "Patients with RA have significantly higher levels of MCP-1/CCL2 in synovial fluid compared to patients with osteoarthritis or other forms of arthritis." (PMID 40255565, 2025). "Conversely, intraarticular injection of CCL2 into the affected joints almost completely restored the severity of SAA-accelerated arthritis in LysM-Cre;Nfat5fl/fl mice compared with Nfat5fl/fl mice." (PMID 38426494, 2024). "We demonstrated that surgically implanted 3D woven scaffolds seeded with genome engineered Ccl2-IL1Ra cells mitigated disease activity and completely prevented bone erosions in the K/BxN serum-induced arthritis model." (PMID 36826339, 2023). "Ccl2-IL1Ra constructs significantly mitigated arthritis when mice were challenged with K/BxN serum transfer one week after implantation." (PMID 36826339, 2023). "Rod-shaped hydrogel constructs containing Ccl2-IL1Ra cells subcutaneously implanted in mice using a wide bore needle significantly mitigated K/BxN serum transfer arthritis, with nearly complete abolishment of disease severity in the front paws." (PMID 36826339, 2023). "Another selective BTK inhibitor, CGI1746, has been reported to reduce CCL2 levels from macrophages in myeloid cell‐dependent arthritis by blocking trans‐phosphorylation of BTK Tyr551 and subsequent auto‐phosphorylation at Tyr223." (PMID 34897650, 2022). "In animal models of arthritis tofacitinib treatment has led to decreased levels of circulating IL-6, IL-8, CCL2, and CXCL10." (PMID 36124688, 2022). "Among the therapeutic options, inhibition of the CCL2/CCR2 chemokine axis holds great promise for controlling chronic painful arthritis." (PMID 33757529, 2021). "So far, results suggest the role of CCL2 chemotaxis in homing and increased activity of OCPs in arthritis." (PMID 34925336, 2021).
Arthritis (continued). "To further validate the mechanism by which MFK902 suppressed arthritis progression, we examined the transcript expression of chemokines (CCL2), adhesion molecules (VCAM-1), MMPs (MMP-1 and -3), and RANKL by semi-quantitative RT-PCR." (PMID 27741237, 2016). "Here, we found that γδ17 cells are the main producers of IL-17 in joints of Il1rn−/− mice, and that recruitment of CCR2+ γδ T cells to the joints via induction of CCL2 by CD4+ T cells is important for the development of arthritis." (PMID 26108163, 2015). "Anti-CCL2 mAb treatment significantly suppressed development of arthritis in Il17g/gIl1rn−/− mice, suggesting an important role for CCL2 in pathogenesis." (PMID 26108163, 2015). "Consistent with our findings, previous studies have shown increased CCL2 production from infiltrating T cells in neoplasia/cancer and infiltrating leukocytes in arthritis." (PMID 25501574, 2014). "All of the analyzed chemokines (CXCL2, CXCL10, and CCL2) peaked at 24 hours after arthritis induction." (PMID 22676339, 2012). "Treatment with CCL2 antagonist before disease onset in an MRL/lpr mouse model of arthritis was shown to prevent the onset of arthritis." (PMID 23185512, 2012). "Recently, administration of EGCG markedly diminished the severity of collagen induced arthritis, macrophage infiltration, and the amount of CCL2-synthesizing osteoblasts." (PMID 21682898, 2011). "Moreover, in a murine model of virus-induced arthritis and myositis, treatment with bindarit, an inhibitor of CCL2/MCP-1 production, impaired the macrophage migration and significantly reduced muscle and joint inflammation." (PMID 41305491, 2025). "Based on these findings, we examined CCL2 expression in the SAA-accelerated arthritis model." (PMID 38426494, 2024). "Moreover, in mice with SAA-accelerated arthritis, myeloid-specific depletion of Nfat5 mitigated infiltration of CCL2-expressing cells in the affected joints, particularly in infiltrating macrophages." (PMID 38426494, 2024). "Moreover, in mice implanted with Ccl2-IL1Ra constructs for 28-weeks, the arthritis clinical scores were similar to those animals challenged with K/BxN serum after one week of implantation, underscoring the long-term activity of these constructs in vivo." (PMID 36826339, 2023). "Furthermore, it is highly migratory toward the CCL2 chemokine increased in the joints during the arthritis development." (PMID 36300108, 2022). "Functional enrichment further supported that the primed genes are heavily involved in inflammatory response, arthritis-promoting functions (Ccl2, Cxcl5, Sphk1) and, interestingly, Wnt pathway (Bmp2, Rspo3, Cd44) and stem cell differentiation (Sox5, Nrp2, Cdk6)." (PMID 35879783, 2022). "Likewise, in preclinical models of arthritis, both CCL2 and CCR2 were found to be upregulated in joints and peripheral tissues and to drive monocyte/macrophage recruitment and inflammation." (PMID 33757529, 2021). "Similar to spleen OCPs, the periarticular CCR2hi subset is strongly induced by arthritis, which prompts us to hypothesize that these OCPs may be the infiltrating population attracted through the CCL2 signal from the circulatory pool released by spleen." (PMID 34925336, 2021). "We then analyzed the expression of corresponding ligands and found a decrease of CX3CL1 expression particularly in PBM and TMT, while the expression of CCL2 was significantly increased in both medullary and extramedullary tissues of mice with arthritis in comparison to control." (PMID 34925336, 2021). "Therefore, addition of CCL2/CCR2 blockade early in the course of arthritis is a promising approach to reduce bone pathology." (PMID 34925336, 2021). "Increased joint CCL2 levels are also detected in murine arthritis models." (PMID 30937315, 2019).
Arthritis (continued). "Single-factor analyses revealed that low education, higher BMI, lower prevalence of arthritis, higher number of NPSLE syndromes, IgG anti-cardiolipin antibodies in serum, and increased levels of CCL2 in cerebrospinal fluid were associated with cognitive dysfunction." (PMID 29723220, 2018). "An antagonist of CCL2 suppresses arthritis in the MRL-lpr mouse model." (PMID 16805906, 2006). "Other investigators have shown that an antagonist to CCL2 suppressed arthritis in a murine model." (PMID 16277688, 2005). "Moreover, gene expression analysis of cultured OCPs showed that osteoclast-differentiation genes (c-Fos, CD115/c-Fms, and Rank) and chemokine CCL2 are induced in the CCR2lo subset of both adjuvant-treated and arthritic groups, whereas arthritis-specific enhancement was observed in CCR2hi OCPs." (PMID 34925336, 2021). "Previous mouse and human studies indicated that CCL2 plays a role in immune-cell infiltration of tissues during immune-mediated inflammatory diseases and high stimulation of CCL2 expression in CCR2hi OCPs by arthritis suggests that it can act in an autocrine manner on osteoclast lineage cells." (PMID 34925336, 2021). "Analysis of adjuvant-induced arthritis(AIA) in IL6+/+ and IL6−/− mice demonstrated that IL6 deficiency is associated with reduced synovial infiltration and is accompanied by a defect in both CCL2 expression and the recruitment of leukocytes bearing the CCL2 receptor CCR2." (PMID 33126846, 2020). "In addition, administration of a neutralizing anti-CCL2 antibody reduced ankle swelling in the rat CIA model, CCL3-deficient mice exhibited milder arthritis induced by an anti-type II collagen mAb and treatment with polyclonal anti-CCL5 antibody ameliorated adjuvant-induced arthritis in rats." (PMID 30053130, 2018). "However, the decreased CCL-2 expression seen in the arthritis group may be a reflection of the chronicity of our model." (PMID 28740214, 2017). "A case in point is the high expression of CCL2 that was reported in joints of arthritis-susceptible C3H mice, which contrasts with the finding that CCL2-receptor deficiency did not reduce arthritis severity, whereas mice deficient in KC receptor developed low-severity of Lyme arthritis." (PMID 23024745, 2012). "In general, from studies using human patient data and animal models of alphaviral arthritis, acute alphaviral-induced arthritis is hallmarked by increased levels of IFNα/β, IFNγ, TNFα, IL-6, IL-1, IP-10, IL-12, IL-15 and CXCL9MCP-1 (CCL2), and MIF-I." (PMID 41442410, 2026). "In an equine IL-1β-induced carpal synovitis model, CCL2, CCL3, CCL5, and CCL11 were identified as sensitive biomarkers during the early stages of joint inflammation (synovitis), exhibiting temporal variations in their response." (PMID 40496923, 2025). "Injection of IL-6 into the affected joints also almost completely reversed arthritis reduction by NFAT5 deficiency, suggesting that IL-6, in addition to CCL2, mediates the progression of SAA/NFAT5 axis–dependent arthritis." (PMID 38426494, 2024). "Another study employing a mouse CIA model revealed that EGCG (administered intraperitoneally daily at 20 mg/kg) ameliorated arthritis and macrophage infiltration while reducing the number of osteoblasts synthesizing MCP-1/CCL2." (PMID 38377032, 2024). "These inflammatory markers also correlate with SLEDAI-2K, levels of dsDNA (CCL2, CXCL10), the presence of lupus nephritis (CCL2, CXCL10, and TNF-α), and arthritis (IL6)." (PMID 38881906, 2024). "Using an online Venn diagram tool, we then screened four genes related to dysregulated genes shared by TGT’s active ingredients and SLE and arthritis, including NLRC3, CD96, CCL2, and TLR1." (PMID 37312878, 2023). "Several studies have shown increased levels of MCP-1/CCL2 in synovial tissue and fluids, as well as in the sera and plasma of RA patients versus osteoarthritis or other arthritis patients." (PMID 36768186, 2023).
Arthritis (continued). "By contrast, the mRNA expression of MCP-1 (CCL-2) and MIP-1α (CCL-3) was unchanged whatever the phase of arthritis." (PMID 35488311, 2022). "Based on the proven importance of the CCL2/CCR2 axis in mouse and human OCP migration, we propose the addition of CCL2/CCR2 blockade early at the course of arthritis as a promising approach to reduce osteoresorptive damage." (PMID 34925336, 2021). "Alongside reducing clinical symptoms of arthritis and synovitis, as already described for CCR2/CCL2 blockade, SMI alone or in combination with MTX showed a decrease in bone loss, and the reduction of myeloid lineage cell accumulation locally and in spleen." (PMID 34925336, 2021). "Taken together, these findings indicate that the sFasL–DR5 interaction promotes arthritis by regulating the CX3CL1–CX3CR1 axis, which increases CCL2, CCL3, and CXCL10 production by CX3CR1+ immune cells." (PMID 34223817, 2021). "The WT, Faslpr/lpr, and Fas–/– mice developed autoantibody-induced arthritis (AIA), whereas the Faslgld/gld mice exhibited attenuation of joint swelling and expression of Il6, Tnfa, Il1b, Ccl2, and Ccl3." (PMID 34223817, 2021). "Using the flow cytometry-based, predesigned Human Chemokine CBA Kit, we detected higher levels of CCL2, CCL3, CCL4, CCL5, CXCL9, and CXCL10 in arthritis than in CTRL plasma." (PMID 28619088, 2017). "CXCL10 remained elevated throughout the response, whereas CCL2 and CXCL2 had decreased to control levels again by day 14 after arthritis induction." (PMID 22676339, 2012). "Our data suggest that synovial fluid lubricin, in addition to a panel of synovial fluid biomarkers, including TNF-α, CCL2, CCL11 and sGAG, may have potential for elucidating the progression of early joint inflammation." (PMID 33980227, 2021). "Both IL-1β-induced synovitis and intra-articular lavage resulted in transient joint inflammation with elevations in synovial fluid TP, WBC count, and PGE2; however, increases in TNF-α and inflammatory chemokines CCL2, CCL3, CCL5, and CCL11 were predominantly restricted to synovitis joints only." (PMID 33980227, 2021). "For Ross River virus (RRV) induced arthritis, it was speculated that inhibition of rheumatic disease with PPS treatment was due to a reduction in IL-6 and CCL2." (PMID 34492036, 2021). "Thus, SFs explant cultures from animals undergoing experimental arthritis were examined for ARNO-dependent expression of IL-6, CCL2 and MMP3." (PMID 35095899, 2021). "Non-MHC genes that influence rat PIA arthritis severity include TNFα, IL-1β, IL-6, IL-17, and CCL-2, and joint damaging MMPs." (PMID 29145473, 2017). "The upregulated expression of TNF-α, IL-1α, IL-1β, IL-4R, P-selectin, MIP-1α (CCL3), MCP-1 (CCL2), NOS2 and NOS3 demonstrated in the present study is in agreement with previous observations of the dependency of the rat SCW-induced arthritis model on these mediators." (PMID 15642130, 2005). "For instance, in systemic sclerosis and psoriasis, dysregulated genes like CCL2 and CCR7 contribute to fibroblast activation and the infiltration of CD4+ T and NK cells through IL-17 signaling pathway, PPAR signaling pathway, leading to skin involvement and arthritis." (PMID 40534874, 2025). "We found that MCP-1/CCL2 and IL-6 were significantly lower in SSR240612-treated WT mouse arthritic ankle homogenates in comparison with vehicle-treated WT mice, suggesting that B1R plays an important role in the expression of these cytokines in K/BxN serum–induced arthritis." (PMID 35439173, 2022). "In the absence of CCL2, no increase in arthritis severity could be observed under voluntary running conditions." (PMID 30397205, 2018). "Genetic ablation of CCL2 or pharmacologic targeting of its receptor CCR2 abates mechanically-induced exacerbation of arthritis, indicating that stress-induced chemokine release by mesenchymal cells and chemo-attraction of monocytes determines preferential homing of arthritis to certain hot spots." (PMID 30397205, 2018).
Arthritis (continued). "Overall, these results demonstrate that high levels of IL-6/sIL-6R, as those present in joints of patients with arthritis, may contribute to the amplification of the inflammatory response enhancing the production of IL-1β, CXCL8 and CCL2 by SFMCs and by RA synoviocytes." (PMID 25271853, 2014). "Thus, the treatment of JWH133 could suppress other inflammatory mediators than IL-6, CCL2 and MMP-3, which are involved in pathology of the arthritis." (PMID 25115332, 2014). "Moreover, improvement or resolution of arthritis in murine models has been seen after treatment with antibodies to macrophage-derived angiogenic chemokines, including IL-8, ENA-78/CXCL5, MIP-1α/CCL3, MCP-1/CCL2, and fractalkine." (PMID 23725043, 2013). "Notably, when GFP+ γδ T cells were gated, CCR2 was expressed at similar levels even in cells from anti-CCL2 mAb-treated non-arthritic mouse joints, suggesting that CCR2 expression in γδ17 cells is required for the development of arthritis." (PMID 26108163, 2015). "Although our CCL2 inhibition and transfer experiments suggested that LN Vγ6+ γδ T cells capable of producing IL-17 were recruited to joints (where they induced arthritis) via CCR2–CCL2 interaction, development of arthritis was not completely suppressed by treatment with anti-CCL2 mAb." (PMID 26108163, 2015).